TMPRSS2 (transmembrane serine protease 2)
Diseases named in the same sentence as TMPRSS2 in open-access papers (continued):
Sharing a sentence is not in itself a finding about the gene and the disease.
cancer (continued). "Mohamed and colleagues screened small-molecule libraries for inhibition of ERG protein in TMPRSS2-ERG harboring VCaP cells and identified a small molecule that selectively inhibits erg-positive cancer cell growth." (PMID 33634124, 2021). "We found that TMPRSS2, SLC6A19, ATGR2, AGT, ACE2, and ACE1 had >5% CNV amplification or deletion in 33 cancers." (PMID 34458283, 2021). "Their cancer origins are defined by the presence of changes to PTEN status, overexpression of c-myc, the presence and expression of TMPRSS2-ERG fusion genes and a cancer-like CpG methylation profile." (PMID 33477370, 2021). "In our analysis, elevation of ACE2, TMPRSS2, and CTSL in cancer vs. normal tissue was observed in many of the tissues examined, including many non-respiratory tract tissues." (PMID 33633121, 2021). "From the results above, it can be seen that two cancers, COAD and READ, highly express both ACE2 and TMPRSS2." (PMID 34257580, 2021). "Recall, all of these smoking-related cancers exhibited above average expression of ACE2 and TMPRSS2 amongst the 20 cancer types analyzed and the rank expression of ACE2 was increased in these malignant tissues compared to their normal tissue counterparts." (PMID 33633121, 2021). "A pan-cancer analysis found that ACE2 and TMPRSS2 are generally expressed less in tumors relative to normal tissue and that digestive organs (both tumor and normal samples) have the highest expression." (PMID 34071688, 2021). "The CoV receptors tended to show a high correlation with immune signatures in most cancer types, though ACE2 and TMPRSS2 exhibited weaker correlations than other receptors." (PMID 33330620, 2020). "Here, we performed a profiling analysis on expression level of a novel SARS-CoV-2 receptor TMPRSS2 and an anti-virus protein IFITM in healthy individuals and patients with pan-cancers." (PMID 33061814, 2020). "In human PCa tissues, we correlated CaSR expression with cancer cell proliferation and ERG expression that reflect the presence of the fusion gene TMPRSS2-ERG (observed in around half of PCa cases)." (PMID 32252342, 2020). "Data on ERG expression obtained by IHC and on transmembrane protease, serine 2:ETS‐related gene fusion (TMPRSS2:ERG) rearrangement obtained by FISH were available from 7935 and from 5360 cancers with interpretable CTCF staining results." (PMID 31736271, 2020). "Therefore, we suggested that IFITM3 could be used as an indicator of the susceptibility of SARS-CoV-2, not just ACE2 and TMPRSS2 in cancer patients." (PMID 33061814, 2020). "In this study, we did landscape profiling of CoV receptors (viz ACE2, TMPRSS2, ANPEP, ENPEP, and DPP4) in various normal and cancer cells." (PMID 33330620, 2020). "In summary, we have discovered that sGC is a novel transcriptional target of TMPRSS2-ERG in PCa cells, and showed that the sGC-mediated NO-cGMP pathway was a critical downstream effector of ERG in promoting cancer cell proliferation and tumorigenesis." (PMID 30718921, 2019). "TMPRSS2 is androgen responsive, and its translocation leads to androgen regulation of ETS oncogenes, which in turn act as cancer drivers." (PMID 30120411, 2019). "A multi-center study of TMPRSS2:ERG (T2-ERG) and PCA3 in post-DRE urine from 1312 men showed significant improvement over serum PSA for the detection of clinically-relevant cancer at biopsy." (PMID 31013716, 2019). "CHEK2 and CDKN2A are known tumor suppressors, and TMPRSS2 and ERG are frequently involved in translocation events forming fusion oncogenes in certain cancers." (PMID 30736820, 2019).
cancer (continued). "We found potentially druggable fusions across 29 cancer types, with major recurrent druggable targets in PRAD (TMPRSS2, 205 samples), THCA (RET, 33 samples), and LAML (PML–RARA, 16 samples)." (PMID 29617662, 2018). "Having discovered a strong correlation between TMPRSS2-ERG fusion and PDE4D7 expression, we then set out to ascertain if cancer aggressiveness is correlated with PDE4D7 expression." (PMID 26575822, 2015). "It has been suggested that urinary PCA3 and TMPRSS2:ERG fusion tests and serum PHI correlate to cancer aggressiveness-related pathological criteria at prostatectomy." (PMID 25079439, 2014). "In summary, we evaluated both primary cancer patients and Met/CRPC patients for the presence of TMPRSS2/ERG rearrangements, AR gene copy number gain, and PTEN deletion using a three-marker FISH panel." (PMID 24098661, 2013). "The homogeneous distribution of the TMPRSS2-ERG fusion and its presence in 19% of high-grade prostatic intraepithelial neoplasia (PIN) lesions adjacent to cancer foci suggests that this fusion is an early event in the development of invasive PCa." (PMID 23708091, 2013). "Among the 34 primary cancer patients with data available from all three markers, 6 of the 8 individuals with PTEN deletion (75%) also showed an abnormal TMPRSS2/ERG FISH result." (PMID 24098661, 2013). "Further studies have shown a role for TMPRSS2/ERG fusion in tumorigenesis in terms of proliferation, invasion and cancer initiation and progression." (PMID 21747944, 2011). "The strength of cancer outlier profile analysis was powerfully demonstrated by the identification of the TMPRSS2-ERG fusion oncogene in prostate cancers, considered a major breakthrough in cancer genetics." (PMID 21365010, 2011). "Since its discovery, the TMPRSS2/ERG fusion has been extensively studied in several aspects, including early diagnosis, prognosis, contribution to cancer progression and even as a target for cancer therapy." (PMID 21747944, 2011). "Several studies demonstrated cooperation between TMPRSS2/ERG and other defective pathways in cancer progression." (PMID 21747944, 2011). "Indeed, KLK14 presence was previously identified as a part of the prostate‐cancer‐related protease network, where secreted KLK14 and KLK4 are recruited to membrane protrusions decorated with cell surface‐bound hepsin and TMPRSS2." (PMID 40621923, 2025). "Since TMPRSS2/ERG is present in more than 50% of prostate cancer tumors, its presence in urine may predict the presence of cancer." (PMID 40115018, 2025). "Treatment of cancer patients infected with SARS‐CoV‐2 by targeting ACE2 and TMPRSS2." (PMID 40145441, 2025). "MTAP staining was significantly stronger in cancers harboring the TMPRSS2:ERG fusion than in ERG fusion negative tumors (p < 0.0001)." (PMID 40554389, 2025). "We also focused on the molecular mechanisms by which SARS-CoV-2 may facilitate cancer progression, including the roles of angiotensin-converting enzyme 2 (ACE2), transmembrane serine protease 2 (TMPRSS2), and FURIN." (PMID 39350850, 2024). "On the other hand, the role of ACE2 and TMPRSS2 in cancer during SARS-CoV-2 infection should be explored to understand the severe infectivity and high mortality rates in respective patients suffering from various types of cancer." (PMID 37809955, 2023). "Early PCCs and PDOs derived from the tissues of PCa patients expressed prostate basal and luminal epithelial markers, as well as cancer markers AMACR, TMPRSS2-ERG, and EZH2, the latter being a promising candidate to mark the transition from the indolent to aggressive PCa." (PMID 36769153, 2023). "PCaT samples and derived PDOs expressed cancer markers AMACR, EZH2 and TMPRSS2-ERG." (PMID 36769153, 2023). "We proposed cancer tissues had higher mRNA expression of ACE2 and TMPRSS2 compared to normal tissues in general and may be more susceptible to SARS-CoV-2." (PMID 36451247, 2022).
cancer (continued). "We next investigated the protein stability of TMPRSS2 protein using cycloheximide (CHX) treatment in the presence or absence of CD treatment in 22RV1 cancer cells." (PMID 36364238, 2022). "TMPRSS2, rather, has been reported for its contribution to severe acute respiratory syndrome coronavirus 2 (SARS-CoV-2) infection, but recently its role in different types of cancers was investigated." (PMID 35841413, 2022). "However, this time, we focused more on the fusion of exon 1 of TMPRSS2 to exon 4/5 of ERG, which is the most abundantly found rearrangement in T:E fusion-positive cancer, as a way to solidly establish T:E fusion-positive cancer." (PMID 36579559, 2022). "In cancers, we detected ACE2 and TMPRSS2 at the biliary pole of tumor hepatocytes." (PMID 35115564, 2022). "Additionally, we assessed TMPRSS2 expression in multiple cancer cell lines based on the CCLE database and found that TMPRSS2 expression was high in COAD, BRCA, PAAD, STAD and PRAD cells but low in AML, MESO, ALL and LUSC cells." (PMID 35017320, 2022). "In this study, we have pre-screened and ranked human cancer cell lines of the Leibniz Institute German Collection of Microorganisms and Cell Cultures (DSMZ) for ACE2 and TMPRSS2 expression within the rich resource Cancer Cell Line Encyclopedia (CCLE) publicly available RNA-seq data." (PMID 34339474, 2021). "Also, many molecular alterations including TMPRSS2-ERG fusions, chromoplexy and PTEN alterations were found in GG1 cancers, as well as higher grade cancers." (PMID 34257593, 2021). "The association of high JUP protein expression and biochemical recurrence was mainly driven by the subset of TMPRSS2:ERG fusion‐negative cancers (P = 0.0003) and not seen in the ERG fusion‐positive subset (P = 0.258)." (PMID 33533127, 2021). "Interestingly, TMPRSS2 positively correlated with SRC in the pancreatic tissues in mixed healthy and cancer datasets." (PMID 33796097, 2021). "In attempts to gain better insights into the role of NRP1 and TMPRSS1 in cancers, the survival curve of cancer patients with differential expression level of NRP1 or TMPRSS2 was analyzed with the Kalpan-Meier plotter, a large database combining information from GEO, EGA and TCGA." (PMID 34168096, 2021). "They concluded that cancer patients overall have an increased risk of SARS-CoV-2 infections than non-cancer patients, however, details on TMPRSS2:ERG patient status are missing." (PMID 33243086, 2020). "Specifically, ACE2, TMPRSS2, CLEC4M, DPP4 and transmembrane protease serine 11D (TMPRSS11D) were analyzed by assessing their RNA expression levels in different body districts and in different cancer types." (PMID 32970391, 2020). "PNUTS staining was significantly more prevalent in cancers harboring TMPRSS2:ERG rearrangements than in cancer lacking ERG fusions." (PMID 32377272, 2020). "High TFAP2D expression was strongly linked to TMPRSS2:ERG rearrangement and ERG expression: TFAP2D positivity increased from 66.5–73.5% in ERG negative cancers (by IHC or FISH) to 88.2–89.8% in ERG positive cancers (p < 0.0001 each)." (PMID 32143573, 2020). "We next examined the prognostic survival of TMPRSS2 and IFITM3 in patients with cancers by ENCORI." (PMID 33061814, 2020). "Notably, while many known functional fusions, including TMPRSS2-ERG, are restricted to specific cancer types, we observed that most recurrent cases were distributed across multiple cancers." (PMID 33097743, 2020). "Survivin immunostaining was absent in 61% of cancers with TMPRSS2:ERG fusion detected by IHC and 63% of cancers detected by FISH, but only in 32% of cancers without ERG staining and 33% of cancers without ERG rearrangements detected by FISH (P < .0001 each)." (PMID 31893572, 2020). "With age, the frequency of TMPRSS2-ERG fusions decreases, however only in low-grade cancers." (PMID 31366128, 2019).
cancer (continued). "For example, moderate or strong nuclear ELAC2 staining was seen in 48.1% of cancers with TMPRSS2:ERG fusion detected by FISH but in only 31.6% of cancers without such rearrangement (p< 0.0001)." (PMID 31452838, 2019). "PTPN12 staining was seen in 86.4% of TMPRSS2:ERG fusion positive but in only 58.4% of ERG negative cancers." (PMID 31606028, 2019). "There is no study investigating the function of Tmprss2 in the brain besides only one study showing its possibility to mediate cancer pain by acting on trigeminal neurons." (PMID 29643838, 2018). "Our observation that 6 of 42 homogeneously ERG-positive cancer foci had focal 6q15 deletions strongly suggests, that presence of TMPRSS2:ERG fusions does not prevent the development of 6q15 deletions." (PMID 26684029, 2016). "The decreasing prevalence of completely ERG negative foci from 70 % to about 50 % with increasing tumor focus size suggest that subclones with TMPRSS2-ERG fusion develop in about 30 % of initially ERG negative cancer foci." (PMID 27530104, 2016). "That this percentage remains at comparable levels (14–36 %) irrespective of the tumor focus size is not surprising as cancers that were initially ERG positive are unlikely to loose TMPRSS2-ERG fusions during tumor progression." (PMID 27530104, 2016). "The complete absence of focal ERG positivity in 34 cancer foci with 6q15 deletions strongly supports the concept of 6q15 deletions either directly or indirectly preventing tumor cells from developing TMPRSS2:ERG fusions." (PMID 26684029, 2016). "PCA3 and TMPRSS2:ERG had additional independent predictive value for the prediction of PCa detection and progression, although PCA3 was limited in predicting aggressive cancer." (PMID 26339615, 2015). "Elevated VEGFR-1 expression was linked to high Gleason grade and advanced pT stage in TMPRSS2:ERG negative cancers (p = 0.0008 and p = 0.001), while these associations were absent in TMPRSS2:ERG positive cancers." (PMID 25894226, 2015). "Yet we detected TMPRSS2-ERG expression in five samples without evidence of carcinoma foci in the immediate vicinity." (PMID 26294063, 2015). "In total, our data supported the concept that if left untreated or lack of initial therapy, TMPRSS2-ERG PCa will run a more aggressive clinical course than fusion-negative cancer." (PMID 24516518, 2014). "Furthermore, recent studies have shown that TMPRSS2:Erg and EWS-Fli1 fusion proteins also sensitise cancer cells to PARP-1 inhibitors by inducing DNA damage, although these studies did not investigate the accumulation of these proteins." (PMID 23405229, 2013). "In addition, recent findings demonstrated a cooperation between TMPRSS2/ERG fusion and deregulated activity of cancer-related pathways, such as PTEN, PI3-Kinase, and AKT or AR." (PMID 21747944, 2011). "In contrast, none of the cancers with rearrangements of the ETV1 gene exhibited fusions involving TMPRSS2 or the HERV-K retroviral sequence." (PMID 18594527, 2008). "However, in clinical outcome correlations only the presence of a duplication of rearranged ERG together with interstitial deletion of genomic sequences between the tandemly located TMPRSS2 and ERG sequences was correlated with worse cancer-specific death." (PMID 18594527, 2008). "In addition, long-term survivors also have antibodies against proteins known to promote cancer growth, such as PIEZO1, aggressiveness such as TMPRSS2, and Epithelial Mesenchymal Transition such as KIAA1217 or C11orf45, which are biomarkers related to immune checkpoint proteins." (PMID 40887652, 2025). "ACE2 and TMPRSS2 not only mediate SARS‐CoV‐2 infection may also be involved in cancer progression (such as affecting tumor proliferation, matastasis or immune infiltration), and they can be used as targets to treat cancer patients infected with SARS‐CoV‐2." (PMID 40145441, 2025).
cancer (continued). "TMPRSS2 and AXL was down-regulated often in cancers but SCARB1 showed the reverse trends, while all of three was shown to be expressed abnormally more frequently than ACE2 and NRP1, which could not provide an expression patten possibly due to their limited situations." (PMID 36875081, 2023). "Mechanisms of TMPRSS2 downregulation in cancer are not yet known." (PMID 38255667, 2023). "Both TMPRSS2-ERG and EZH2 are included in the Catalogue of Somatic Mutations in Cancer, however the whole-genome sequencing of PCa did not designate these genes as cancer drivers." (PMID 36769153, 2023). "Therefore, we analyzed the prognosis of TMPRSS2 in abnormally expressed cancers using the Kaplan-Meier plotter databases and GEPIA databases, and we found that increased TMPRSS2 expression was correlated with a better prognosis in KIRP, LUAD, UCEC, LIHC, and STAD." (PMID 35558557, 2022). "Besides the expression of TMPRSS2, TMPRSS4, and TRIM31 in GI cancers, we have analysed the expression of these genes in all cancers, and we have found that the expression of these genes is more upregulated in majority of GI cancers than individual other cancer types." (PMID 35970857, 2022). "However, the systematic analysis of TMPRSS2 aberrations has not been characterized in human cancers." (PMID 35281819, 2022). "However, the expression and prognostic value of TMPRSS2 in many cancers have not been clearly defined." (PMID 34951103, 2022). "Although the farther away from the cancer tissue, the closer the tissue is to normal, there may still be abnormal biological behavior of cells in the specimens we adopted, affecting the expression of ACE2 and TMPRSS2." (PMID 34412632, 2021). "Interestingly, most tumor types exhibited weaker ACE2/TMPRSS2 and ACE2/CTSB correlations compared to normal tissue, whereas the ACE2/CTSL and ACE2/FURIN correlations in normal tissue are weaker than that of most cancer types." (PMID 33707526, 2021). "The transcription of TMPRSS2 and ACE2 in major organs could be modulated by systemic androgen deprivation among adult male mice, prompting camostat mesylate and androgen regulation as a therapeutic strategy for cancer patients infected by SARS-CoV-2." (PMID 34399734, 2021). "However, a systematic analysis of aberrant expression of ACE2 and TMPRSS2 was not yet reported in multiple human cancers." (PMID 34257580, 2021). "Furthermore, 62.5% of SARS-CoV-2-required genes containing ACE2, TMPRSS2, ATP6AP1, ATP6V1A, and CCDC22 exhibited a significant upregulation in UCEC relative to normal tissue, while only PIK3C3 showed an obvious downregulation in this cancer." (PMID 35082790, 2021). "Furthermore, the expression levels of ACE2 and TMPRSS2 in different cancers do not always follow the opposite trend." (PMID 34131396, 2021). "Through surveying CCLE (cancer cell line encyclopedia) expression profiles, we observed remarkably higher mRNA expression levels of both CTSL and FURIN in H2126, potentially indicating TMPRSS2-independent SARS-CoV-2 infection and explaining less efficacy of camostat mesylate in these cells." (PMID 33558541, 2021). "SFRP4 up-regulation was strongly linked to TMPRSS2:ERG rearrangement and ERG expression: Strong SFRP4 positivity increased from 5.6% and 6.3% (by IHC and FISH) in ERG negative cancers to 11.2% and 11.7% in ERG positive cancers (p < 0.0001 each)." (PMID 32677026, 2020). "Its prognostic impact is pronounced, however, in cancers lacking TMPRSS2:ERG fusion." (PMID 31452838, 2019). "Also, the expression of ERG in cancer samples with TMPRSS2-ERG was significantly higher than in cancer samples without the fusion transcript (P < 0.001)." (PMID 31537872, 2019). "Interestingly, one cancer sample had a high expression of ERG without any detectable TMPRSS2-ERG transcript." (PMID 31537872, 2019). "However, TMPRSS2-ERG is absent in 50% of cancers, and therefore it must be multiplexed with other biomarkers such as PCA3." (PMID 29682400, 2017).